RSPO2 (R-spondin 2)
Diseases named in the same sentence as RSPO2 in open-access papers (continued):
Sharing a sentence is not in itself a finding about the gene and the disease.
prostate carcinoma (7 papers, 2016 to 2025). A carcinoma that arises from epithelial cells of the prostate gland. "Moreover, RSPO2 gene fusions associated with elevated RSPO2 expression have been identified in prostate cancer patients, that were mutually exclusive with APC and CTNNB1 mutations." (PMID 34663878, 2021). "We also confirmed the genomic observations of previous studies in which RSPO2 is a recurrently amplified gene with limited deletions in prostate cancers." (PMID 37059746, 2023). "RSPO2 gene amplification occurs in up to 6.5% and 21% of primary and advanced prostate cancers, respectively, and has a strong tendency to co-occur with FZD6 overexpression." (PMID 35204808, 2022). "Antagonists of both these genes, R-Spondin 2 (RSPO2) and R-Spondin 3 (RSPO3) fusions potentiate the Wnt/β-catenin signaling and have been linked with prostate cancer." (PMID 35201496, 2021). "In human prostate cancer, PTEN loss is an early tumorigenic lesion, while Wnt-pathway activation through aberrations in APC, CTNNB1, RNF43, and RSPO2 are found in metastatic castration-resistant cancer, suggesting they are associated with tumor progression." (PMID 27536883, 2016). "Altogether, there is a need to functionally explore RSPO2 in differentiation models of prostate cancer, which, to our knowledge, may be sparse." (PMID 40711886, 2025). "Thus, RSPO2 upregulation in prostate cancer provides a direct mechanism for elevated Wnt signaling that can promote tumor growth." (PMID 35204808, 2022). "Our findings revealed that RSPO2 alterations occurred more frequently than those in other family members, as well as canonical Wnt regulators CTNNB1 and APC, providing insight into its potential significance in prostate cancer progression." (PMID 40711886, 2025). "It was known that AR amplification sensitizes prostate cancers to low levels of androgen, that PI3K (PIK3CA/B) and Wnt (RSPO2) pathways can bypass the AR function for cell proliferation, and that CCND1 regulates the cell cycle; therefore, all five genes are involved in mCRPC." (PMID 34439974, 2021). "Additionally, we examined the effects of RSPO2 overexpression in both androgen receptor-positive (AR+) and androgen receptor-negative (AR-) prostate cancer cell lines." (PMID 40711886, 2025). "Unlike in CRC, these prostate cancer cases harbored fusions of RSPO2 with GRHL2 instead of EIF3E." (PMID 34663878, 2021).
gastric cancer (6 papers, 2018 to 2025). A primary or metastatic malignant neoplasm involving the stomach. "Suppression of Rspo2 expression levels by siRNA significantly inhibited cell migration and invasion in gastric cancer cell lines (AGS and BGC-823)." (PMID 37946278, 2023). "RSPO2 has also been shown to promote EMT of gastric cancer by regulating the β-catenin signal in gastric cancer cells." (PMID 35281864, 2022). "5-Aza-CdR reduced the hypermethylation level of RSPO2 and induced its re-expression in gastric cancer cell lines." (PMID 34175894, 2021). "Moreover, the decreased expression of LGR5 and β-catenin were observed in human gastric cancer by silencing Rspo2." (PMID 37946278, 2023). "RSPO2 has been found to enhance WNT/β-catenin signaling, thereby promoting the invasion and migration of gastric cancer (GC) cells." (PMID 40951343, 2025). "In the GA007 gastric cancer sample, we identified a fusion between the EMC2 gene exon 1 (NM_014673.4) and the RSPO2 exon 2 (NM_178565.4)." (PMID 30250044, 2018).
tetra-amelia syndrome (5 papers, 2020 to 2025). "The recessive mutation in RSPO2 gene could cause tetra-amelia syndrome, which is characterized by lung aplasia and the total absence of the four limbs." (PMID 33391332, 2020). "To date, biallelic loss-of-function mutations in two genes have been reported to be causally associated with human tetra-amelia syndrome, WNT3 and RSPO2." (PMID 40723430, 2025). "To date, TBX5 has been associated with upper amelia, TBX4 with lower amelia, and WNT3, WNT7A and RSPO2 with tetra-amelia syndromes in humans (and cattle, for RSPO2)." (PMID 40131457, 2025). "Human genetic studies revealed that RSPO1 is critical for ovarian development, and RSPO2 mutation leads to tetra-amelia syndrome including lung aplasia and a lack of limbs, while RSPO4 is necessary for human nail formation." (PMID 34847079, 2022).
neuroblastoma (4 papers, 2018 to 2022). Neuroblastoma (NB) is the most common solid, extracranial childhood tumor. "Consistently with the convergence of Wnt and BMP signaling on MSX proteins, GSEA analysis confirmed a profound effect of Wnt3a/Rspo2 on the MSX1-regulated neuroblastoma transcriptome." (PMID 32210188, 2020). "This prompted us to define the neuroblastoma-specific Wnt3a/Rspo2-driven transcriptome using RNA sequencing, and characterise the accompanying changes in cell biology." (PMID 29505958, 2018). "These analyses, together with our evaluation of Wnt3a/Rspo2 effects on neuroblastoma cell biology, reveal that Wnt regulates recently discovered drivers of differentiation such as EPAS1 and BMP4 in cell lines that undergo differentiation." (PMID 29505958, 2018). "We also evaluated the effects of Wnt3a/Rspo2 treatment on a third LGR5-positive neuroblastoma cell line, SK-N-AS." (PMID 29505958, 2018). "However, our previous work demonstrated that Wnt3a/Rspo2 treatment of some neuroblastoma cell lines can, paradoxically, decrease c-MYC and MYCN proteins." (PMID 29505958, 2018). "Based on our recent identification of genes regulated by the Wnt ligand Wnt3a and Wnt agonist R-spondin 2 in an NB cell-line, we assess transcriptional and signaling pathways, which require further investigation in the contexts of NC development and neuroblastoma." (PMID 31040767, 2019). "We previously demonstrated that Wnt/β-catenin signaling can have cell-type-specific effects on neuroblastoma phenotypes, including growth inhibition and differentiation, and that BMP4 mRNA and protein were induced by Wnt3a/Rspo2." (PMID 32210188, 2020). "Analysis of genes that are increased with retinoic acid induced differentiation of neuroblastoma cells (NGRF, NF68, NTRK1, SYP, MAP2, NEFM, DKK2) showed that all were elevated after 72 hours Wnt3a/Rspo2 treatment." (PMID 29505958, 2018). "In our RNA-seq analysis of Wnt3a/Rspo2-treated neuroblastoma cells, BMP4 was amongst the most highly induced genes (>50-fold) and BMP4 protein was also upregulated, leading us to further analyse global effects of Wnt3a/Rspo2-treatment on BMP/TGF gene sets." (PMID 32210188, 2020). "Finally, treatment of N2A cells with RSPO2, a leucine rich repeat-containing G-protein coupled receptor (LGR) ligand that has been shown to amplify Wnt signal in a subset of neuroblastoma cells, did not induce significant changes in either Tcf7L2, Paupar or Pax6." (PMID 35709096, 2022).
Anonychia (3 papers, 2011 to 2025). Aplasia of the nail. "For example, alterations in RSPO4 activity have been reported to cause anonychia in humans, whereas disruption of Rspo2 or Rspo3 in mice affects development of several different systems (skeletal, respiratory or placenta defects)." (PMID 21297984, 2011). "Murine models with conditional Rspo2 [R-spondin 2, which, like RSPO4 (R-spondin 4), belongs to the R-spondin protein family] knockouts recapitulate human anonychia, further supporting pathogenicity." (PMID 40620857, 2025).
colorectal tumors (3 papers, 2019 to 2021). "Wnt signaling is ubiquitously activated in colorectal tumors and driver mutations are identified in genes such as APC, CTNNB1, RNF43 and R-spondin (RSPO2/3)." (PMID 33202731, 2020). "Tumours harbouring gene fusions involving RSPO2 and RSPO3 were found to occur in around 10% of colorectal tumours and result in upregulation of RSPO2 or RSPO3 expression." (PMID 30792270, 2019). "Moreover, RSPO2 was shown to inhibit the growth of colorectal tumors through LGR5-dependent WNT signaling." (PMID 33807916, 2021). "Approximately 15% of colorectal tumors have ligand-dependent alterations in the Wnt signaling pathway, affecting RNF43 or RSPO2/3." (PMID 33202731, 2020).
idiopathic pulmonary fibrosis (3 papers, 2022 to 2026). Idiopathic pulmonary fibrosis (IPF) is a nonneoplastic pulmonary disease that is characterized by the formation of scar tissue within the lungs in the absence of any known cause. "Interestingly, it was recently reported that RSPO2 protein expression is detected in bronchiolar and alveolar epithelial cells in human idiopathic pulmonary fibrosis lungs, and RSPO2 has anti-proliferative and apoptotic effects on lung fibroblasts." (PMID 35328508, 2022). "Conversely, in idiopathic pulmonary fibrosis (IPF), RSPO2 and its receptor LGR6 are upregulated in fibroblasts and epithelial cells." (PMID 41541657, 2026).
Insulin resistance (3 papers, 2022 to 2026). Increased resistance towards insulin, that is, diminished effectiveness of insulin in reducing blood glucose levels. "In mice, elevated plasma RSPO2 levels were additionally associated with insulin resistance, also plasma RSPO2 levels in humans (specifically in men only) correlated with insulin resistance and fat distribution (elevated RSPO2 levels were associated with obesity)." (PMID 35707461, 2022). "Overexpression of RSPO2, specifically in ingWAT, confirmed our finding that RSPO2 can inhibit adipocyte formation and cause adipocyte hypertrophy, with a trend toward development of insulin resistance." (PMID 35027768, 2022). "Increased circulating RSPO2 in mice leads to adipose tissue hypertrophy and insulin resistance and increased RSPO2 levels in male obese individuals correlate with impaired glucose homeostasis." (PMID 35027768, 2022). "We propose that a combination of these factors contribute to the development of insulin resistance in RSPO2-overexpressing mice." (PMID 35027768, 2022). "Besides reducing adipocyte numbers, RSPO2 facilitated macrophage recruitment into ingWAT, which might contribute to the observed insulin resistance." (PMID 35027768, 2022).
lung adenocarcinoma (3 papers, 2017 to 2024). A carcinoma that arises from the lung and is characterized by the presence of malignant glandular epithelial cells. "The downregulation of RSPO2 by miR-196b-5p also provided a new theoretical basis for the treatment of lung adenocarcinoma." (PMID 38627774, 2024). "Dysregulated expression of RSPO2 is closely related to the tumor invasiveness and aggressiveness in papillary thyroid cancer, pancreatic cancer and lung adenocarcinoma." (PMID 28350845, 2017). "There are several oncogenic proteins such as EPHA3 and RSPO1, RSPO2, and RSPO3, which are overexpressed in lung adenocarcinomas and lymphoblastic leukemia and define the patient’s survival rates." (PMID 36139498, 2022).
Obesity (3 papers, 2022 to 2023). Accumulation of substantial excess body fat. "Collectively, our data suggest that Rspo2 inhibits adipocyte formation during obesity, which leads to adipocyte hypertrophy and macrophage infiltration into adipose tissue." (PMID 35027768, 2022). "Collectively, these data suggest that Rspo2 inhibits adipocyte formation in HFD-induced obesity." (PMID 35027768, 2022). "HFD mice have more eP3 cells in ingWAT and express higher levels of RSPO2 in circulation and adipose tissue, suggesting that eP3 or RSPO2 might regulate adipose tissue expansion during obesity." (PMID 35027768, 2022). "As Rspo2 inhibits adipocyte formation in vivo, we next investigated, whether Rspo2 influences adipose tissue expansion during obesity." (PMID 35027768, 2022).
pancreatic cancer (3 papers, 2017 to 2018). "In addition, Rspo2 was reported to enhance Wnt signaling and stemness in Wnt responsive pancreatic cancer cells." (PMID 30337838, 2018).
papillary thyroid cancer (3 papers, 2015 to 2017). "Lgr5 and RSPO2 are also associated with tumor aggressiveness, lymph node metastases, and Wnt/β-catenin activation in human papillary thyroid cancer." (PMID 28404917, 2017). "Our data is the first to report that LGR5 and its ligand, RSPO2, are associated with tumor aggressiveness, lymph node metastases, and Wnt/β-catenin activation in human papillary thyroid cancer." (PMID 26416247, 2015).
breast tumors (2 papers, 2021 to 2022). "In breast tumors, RSPO2 and RSPO3 were first identified as being involved in BCa initiation, proliferation, epithelial-mesenchymal transition, and metastasis." (PMID 34847079, 2022). "Overexpression of RSPO2, RSPO3, and RSPO4 have been reported in breast tumors, with a particular occurrence in TNBC and being associated with reduced patient survival in case of RSPO2 upregulation." (PMID 34663878, 2021).
colitis (2 papers, 2016 to 2020). Inflammation of the colon. "We previously reported that Rspo2 is a major determinant of susceptibility to Citrobacter rodentium-mediated colitis in mice and recent genome-wide association studies have revealed RSPO3 as a candidate Crohn’s disease-specific inflammatory bowel disease susceptibility gene in humans." (PMID 27046199, 2016). "Together, these results highlight Rspo3 as the dominant R-spondin in DSS colitis and provide evidence that Rspo2 and Rspo3 may respond to specific pathogenic and inflammatory signals that differ between the two colonic inflammation models." (PMID 27046199, 2016). "R-spondins were found to be highly modulated during inflammation, with notably robust upregulation of Rspo2 expression during C. rodentium infection in susceptible mice and upregulation of Rspo3 expression during DSS colitis." (PMID 27046199, 2016).
Dupuytren Contracture (2 papers, 2021). A fibromatosis of the palmar fascia characterized by thickening and contracture of the fibrous bands on the palmar surfaces of the hand and fingers. "In conclusion, SNPs WNT7B rs6519955 and RSPO2 rs611744 are associated with the development of Dupuytren’s contracture: WNT7B rs6519955 TT genotype increases the chances by 3.5-fold, and RSPO2 rs611744 genotype GG appears to attenuate the likelihood of the manifestation of DC nearly twofold." (PMID 34573275, 2021).
lung carcinoma (2 papers, 2020 to 2022). "The physiological relevance of RSPO2 expression in adult lungs is unclear, although RSPO2 has been demonstrated to play a role in idiopathic lung fibrosis and can be used as a biomarker for lung cancer." (PMID 32019591, 2020).
melanoma (2 papers, 2023 to 2024). A malignant, usually aggressive tumor composed of atypical, neoplastic melanocytes. "For the melanoma patient with two tumor sites, three tier-1 genes, namely PSIP1, RSPO2, and SF3B1, were identified in both tumor tissues and ctDNA." (PMID 37878600, 2023).
metastatic disease (2 papers, 2022 to 2025). "This analysis revealed significantly higher expression of PRAME and RSPO2 in metastatic tumors, further supporting their potential role in disease progression." (PMID 40076569, 2025).
thyroid (2 papers, 2017 to 2022). "In summary, we showed that the RSPO2 and GPR48/LGR4 function in thyroid tumorigenesis, particularly in patients with regional tumor progression including LN metastasis." (PMID 29383135, 2017).
acute myeloid leukemia (1 paper, 2022). Acute myeloid leukemia (AML) is a group of neoplasms arising from precursor cells committed to the myeloid cell-line differentiation. "Intriguingly, a recent study showed that the binding of the TSP domain of RSPO2 to the ALK3 receptor inhibited BMP signaling in acute myeloid leukemia (AML) cells." (PMID 36217544, 2022).
adenoma (1 paper, 2023). A neoplasm arising from the epithelium. "An additional exploration of data from familial adenomatous polyposis (FAP) and CRC patients indicated that the epigenetic silencing of RSPO2 is a progressive event that maximizes at mid-late stages in the adenoma to carcinoma sequence." (PMID 37612734, 2023). "To explore whether the epigenetic inactivation of RSPO2 is an early or a late event in the adenoma to carcinoma sequence, we explored a recent publicly available dataset corresponding to normal colon organoids from FAP patients and control samples." (PMID 37612734, 2023). "R-spondin-2 is epigenetically repressed in CRC along the adenoma to carcinoma sequence." (PMID 37612734, 2023). "The fact that the promoter methylation of this gene also displays a gradual increase along the adenoma to carcinoma sequence further suggests that RSPO2 may have a functional role as a potential tumour suppressor gene in CRC tumorigenesis." (PMID 37612734, 2023).
Amelia (1 paper, 2025). Congenital absence (aplasia) of one or more limbs. "In cattle and humans, large deletions or nonsense variants in RSPO2 cause tetra-amelia, characterized by the complete absence of all four limbs and lung aplasia." (PMID 40131457, 2025).
atherosclerosis (1 paper, 2025). A disease characterized by the build-up of fatty material and calcium deposition in the arterial wall resulting in partial or complete occlusion of the arterial lumen. "Therefore, it is tempting to speculate on the beneficial role of hepatocyte RSPO2 in atherosclerosis, in contrast to its detrimental role in vascular cells." (PMID 41300494, 2025). "Therefore, inhibition of Rspo2-induced LGR4 activation and downstream Wnt signaling utilizing recombinant proteins, blocking antibodies, and small molecule inhibitors has the potential to reduce atherosclerosis; however, this possibility requires further investigation." (PMID 41300494, 2025).
benign breast lump (1 paper, 2022). "To examine whether RSPO2/RANKL-DKK1 signaling is specific to bone metastasis patients, we next examined the serological RSPO2, RANKL, and DKK1 levels in benign breast lump patients (n = 9), primary BCa patients (n = 28), and bone metastasis BCa patients (n = 10)." (PMID 34847079, 2022).
chronic lung disease (1 paper, 2022). According to the definitions of the American and British Thoracic Societies, including pulmonary functional tests, X-rays, and CT scans for items such as fibrosis, bronchiectasis, bullae, emphysema, nodular or lymphomatous abnormalities. "Our findings suggest that RSPO2 is a key regulator of lung homeostasis and regeneration and may play a protective role in acute lung tissue damage and chronic lung diseases." (PMID 35328508, 2022). "Our results strongly suggest that RSPO2 plays a key role in the adult lung epithelial stem/progenitor cells during homeostasis and regeneration, and therefore, it may be a potential therapeutic target for chronic lung diseases with reduced regenerative capability." (PMID 35328508, 2022).
cleft lip (1 paper, 2020). Congenital defect in the upper lip where the maxillary prominence fails to merge with the merged medial nasal prominences. "Of note, bilateral cleft lip, a phenotype never observed in Rspo2–/– mice, was observed in some Rspo2–/– mice in a Wnt9b± background (50%, 3/6)." (PMID 32457899, 2020).
corticotropinomas (1 paper, 2024). "In this work, we have shown the significant downregulation of RSPO2 (agonist) and SFRP1 (antagonist) in WNT signaling in USP8-mutant corticotropinomas, which supports our hypothesis on the role of USP8-mutation-altered WNT signaling regulation in these tumors." (PMID 39684597, 2024).